SOX2 (SRY-box transcription factor 2)
Diseases named in the same sentence as SOX2 in open-access papers (continued):
Sharing a sentence is not in itself a finding about the gene and the disease.
tumor (continued). "The expression levels of the Sox2 and Lin28 genes were significantly correlated with tumor size." (PMID 23599755, 2013). "To address this hypothesis, we analyzed the expression levels of CSCs markers ALDH and SOX2 and tumor stroma-associated markers CXCR4, SDF-1, VEGFR1, CD11b and α-sma in primary tumor and metastatic nodules." (PMID 24278179, 2013). "Furthermore, SOX2 knocked down cells showed lower tumor-initiation than that of control siRNA transfected MCAS cells." (PMID 23967051, 2013). "One possibility for the increased castration-resistant tumor formation of the LAPC-4-Sox2 cells is that Sox2 expression may promote a cancer stem/initiating tumor phenotype that would promote tumor xenograft formation." (PMID 23326489, 2013). "Altered expression of Klf4, Sox2, Oct4, Nanog and c-Myc genes indicates the abundance of cancer stem-like cells (CSLCs) in primary tumors that may be key resources for tumor progression and the poor prognosis of HCC." (PMID 23599755, 2013). "Interestingly, immunohistochemical analysis of 122 NPCs showed an invasion front-specific overexpression of nuclear SOX2 in 37 samples compared with the tumor center-specific overexpression of that in 20 samples (P = 0.010)." (PMID 23424657, 2013). "More recently, SOX2 and other embryonic proteins have been hypothesized to identify the tumor stem cell subpopulation within malignancies." (PMID 23544055, 2013). "Furthermore, the tumor tissues formed from HCT116 cells infected with Sox2 exhibited higher ATG10 and ATG8b protein levels compared with tumors from the HCT116 cells infected with mock vector." (PMID 23451179, 2013). "SOX2 expression in tumor is a candidate positive prognostic biomarker for NSCLC patients." (PMID 23990933, 2013). "Furthermore, tumor growth was markedly attenuated in athymic nude mice injected with HCT116 cells infected with Sox2 compared with HCT116 cells infected with mock vector." (PMID 23451179, 2013). "Discovery of these genes’ function in the occurrence of tumor after SOX2 down-regulation and use of combined therapies targeting them and the SOX2 gene may improve the outcome of lung tumor therapy." (PMID 22615765, 2012). "In addition, most of the tumor tissues with high expression level of SOX2 showed both nuclear and cytosol localization of SOX2; in contrast, those tissue with lower expression level of SOX2 always revealed only cytosol localization." (PMID 22615765, 2012). "In addition, the numbers of tumor loci are about 6 times higher (3.3±1.75 vs. 0.57±0.79) in metastases with the mock knock down cells compared to the SOX2 knock down cells." (PMID 22912670, 2012). "This could indicate the cellular ontogenesis of the β-catnc clusters in ACP, whereby SOX2+ve stem cells with long telomeres are initially present but differentiate at later stages of tumour development losing SOX2 expression and shortening their telomeres." (PMID 22349813, 2012). "We further demonstrated that silencing SOX2 could significant decrease the ability of cell migration and invasion in vitro and reduce the ability of tumor metastasis in vivo." (PMID 22912670, 2012). "Since SOX2 is an important transcriptional factor that maintains the function of CSCs, we hypothesized that SOX2 might regulate the transcription of certain oncogenes in tumor cells." (PMID 22615765, 2012). "In some tumor studies, hyaluronan binding to tumor cells promoted Nanog protein in association with CD44 followed by Nanog activation and the expression of pluripotent stem cell regulators such as Rex1 and Sox2." (PMID 22400115, 2012). "Recent studies suggested a role of SOX2 in tumor progression." (PMID 22070920, 2011). "Sox3 followed the same expression pattern as Sox2 in all tumor samples examined." (PMID 21483788, 2011).
tumor (continued). "Although SOX2 functions differ between organ systems since transcriptional activation is influenced by the recruitment of tissue-specific transcription factors, SOX2-mediated induction of tumor invasiveness may be a common theme in different tumor entities." (PMID 21276239, 2011). "Absence of SOX2 expression was associated with an advanced T-category (T3 - T4) but reduced rates of locoregional- and distant spread and lower histopathological tumour grades (G2 - G3)." (PMID 22168803, 2011). "While sox2, nanog, and oct4 are required for induction of the pluripotent stem cell phenotype, c-myc expression also correlates with tumor formation and upregulation of this oncogene could trigger the higher tumor initiating potential." (PMID 21602936, 2011). "Further studies are needed to explore whether SOX2 can predict metastatic potential at an early tumor stage." (PMID 21276239, 2011). "We hereby report SOX2 to be expressed in all tissues we analyzed, which is in contrast to previous studies where SOX2 expression has been reported to be restricted to certain tissues (among others neural, stem cell, or tumor tissue)." (PMID 22190969, 2011). "Therefore, we used three factors (Oct3/4, Klf4, and Sox2), eliminating c-Myc, with a special emphasis on escape from tumor development." (PMID 21789202, 2011). "Several lines of evidence suggest an oncogenic role of SOX2 in tumor progression." (PMID 22070920, 2011). "Taken together, Oct4 or Sox2 might play an important role in carcinogenesis and tumor progression and may be used as an indicator of the patient prognosis." (PMID 20937145, 2010). "Therefore, we implanted transduced cells in vivo to assess the effect of Sox2 over-expression on tumor formation and growth in immunocompromised mice injected subcutaneously." (PMID 20126410, 2010). "Altogether, SOX2 could participate in tumor progression at several steps during carcinogenesis by promoting both tumor cell de-differentiation and maintenance of a stem/progenitor cell-like phenotype." (PMID 20126410, 2010). "DCUN1D1 and SOX2 may be co-driver genes of 3q26.3 amplification that synergistically modulate different molecular traits and result in a more aggressive tumor phenotype." (PMID 20126410, 2010). "The expression of these genes may, at least in part, explain the increase in invasiveness following 5-Aza-2-deoxycytidine treatment, as both sox-2 and midkine may play roles in tumor progression." (PMID 20019818, 2009). "Expression of SOX2 mRNA was further investigated in tumour and normal tissues by real-time PCR." (PMID 17375044, 2007). "In addition, we identified an HLA-A*0201-restricted peptide derived from SOX2, which proved to be effective in activating tumour-directed CTL responses." (PMID 17375044, 2007). "Furthermore, we investigated GBM tissue from 11 patients for expression of SOX2 protein in tumour cells in situ, using immunohistochemistry." (PMID 17375044, 2007). "In addition, both genotypes showed similar high levels of Ki-67 expression, suggesting SOX2 loss did not impair tumor growth, consistent with the survival curve." (PMID 41266112, 2026). "On the basis of the increased SOX2 gene expression and the significant higher percentage of SOX2-positive cells and higher H-score in EB-cSCC than in the UV-induced cSCC, we suggest that SOX2 could also have a key role in the tumor initiation and aggressive nature of EB-cSCC." (PMID 41189680, 2026). "Moving forward, it will be critical to identify the core transcriptional and chromatin remodeling dependencies that sustain NC across contexts, and to investigate whether rare SOX2-positive subpopulations contribute to tumor heterogeneity, therapeutic resistance, or recurrence." (PMID 41266112, 2026). "Indeed, ablation of SOX2 in the K14+ lineage delayed tumour growth in this model." (PMID 41507151, 2026).
tumor (continued). "However, SOX2 is uniquely upregulated in progenitor-derived tumours and is expressed in 20% of human cSCC, indicating it might mark tumours arising from committed progenitors." (PMID 41507151, 2026). "Notably, autopsy tissue analysis revealed SOX2 positive tumor cells in the perivascular spaces." (PMID 41510293, 2025). "Finally, IHC staining for the stemness‐associated TF SOX2 demonstrated reduced expression levels in the xenografts formed by Dot1Li‐treated OVCAR5 cells compared to controls, suggesting that Dot1Li targets CSCs and prevents tumor initiation." (PMID 40051293, 2025). "To verify whether monocyte- and macrophage-CM modulate the tumor plasticity of SCC cells, we analyzed the expression of genes associated with epithelial-mesenchymal transition (EPCAM, SOX2), stemness (NANOG, MYC, EZH2), and neuroendocrine differentiation (CHGA, AURKA, MYCN)." (PMID 41259557, 2025). "SOX2 may be a consistent indicator of tumor repopulation following chemotherapy." (PMID 40804837, 2025). "Furthermore, double-staining for the stem and progenitor cell marker Sox2 and the proliferation marker Ki67 in KD tumor sections, Sox2-positive/Ki67-negative cells dispersed throughout the tissue, supporting the presence of a slow-cycling potential qNSC population (Fig. EV2J)." (PMID 39285246, 2024). "Therefore, we predicted that SOX2 may have a role in tumor immunology and may be a new therapeutic target in PAAD." (PMID 38164286, 2024). "In addition, this tumor frequently displays the robust expression of one or more stem cell markers, such as SOX2, CD34, and SALL4, which can facilitate the differential diagnosis of SMARCA4-deficient non-small cell lung cancer (NSCLC) (SMARCA4-dNSCLC), typically negative for these markers." (PMID 38881888, 2024). "In conclusion, we demonstrated for the first time that Notum upregulated the level of Sox2 byPI3K/AKT signaling pathway to promote tumor sphere formation and tumorigenicity in GC and found that Caffeine as Notum inhibitor could effectively abrogated GC spheroids formation but not affect cell growth." (PMID 37749430, 2024). "Therefore, this lineage, called tumor-associated cells with a myeloid-like expression profile (TAMEP), can be separated from microglia and macrophages and is generated by CNS-resident, SOX2-positive progenitors to enhance tumor growth and invasion, stimulating neo-angiogenesis." (PMID 39513861, 2024). "Notably, cetuximab-treated tumours displayed a threefold increase in SOX-2 expression." (PMID 38467828, 2024). "Therefore, STIM1 and SOX2 co-expression in tumor cells and intra-tumoral stroma could contribute to the development of PDAC and AAC." (PMID 38532463, 2024). "Therefore, protein markers, including Nanog, OCT3/4, and SOX2, were detected, as they promote the emergence of CSCs with mesenchymal properties necessary for proliferation and self-renewal, which are required for secondary tumor formation." (PMID 39469631, 2024). "Additionally, Notum knockdown or overexpression could impair or enhance stemness of GC cells by targeting Sox2.Therefore, we concluded that Notum mediated tumor sphere formation and tumorigenicity through upregulation of Sox2 by PI3K/AKT signaling pathway." (PMID 37749430, 2024). "Furthermore, the knockdown of SOX2 partially reversed the proliferation of the tumours." (PMID 37658588, 2023).
tumor (continued). "Furthermore, the presence of such connections in other cellular systems and the known involvement of SOX6 (a paralog of SOX2) in Wnt signaling, strengthens the importance of these findings within the broader context of cell regulation and signaling pathways in the tumor microenvironment." (PMID 38003292, 2023). "To assess whether the upregulation of stem cell transcription factors participate in integrin αvβ3/PI3K/AKT-induced tumor cell proliferation, we measured the gene expression levels of SOX2, Oct3/4, c-Myc, Tert, KLF4 and Nanog in PBS- or FN-treated A549 and Lewis cells by real-time PCR." (PMID 37809806, 2023). "Therefore, we hypothesized that FN facilitates tumor growth through SOX2, as the downstream transcription factor of PI3K/AKT in NSCLC." (PMID 37809806, 2023). "Moreover, C3a exposure stimulates β-catenin and Sox-2, a transcription factor which regulates cell stemness and induces pluripotent stem cells; in fact, C3a receptor silencing led to the down-regulation of β-catenin and Sox-2 with the consequent decrease of tumor volume." (PMID 36675086, 2023). "Moreover, in progressive cases, we suggested that Sox2 expression may be an intrinsic feature of the tumor after its initial diagnosis." (PMID 36836440, 2023). "In CSCs, overexpression of the transcription factor Nanog, in coordination with Oct-4, Sox-2, Bmi-1 and other complexes, enhanced the characteristic expression of CSCs and activated their self-renewal, metastasis, invasion, angiogenesis and drug resistance, thereby reducing tumor cell apoptosis." (PMID 38095348, 2023). "Furthermore, DSCC1 silence could downregulate the expression of multiple biomarkers of stem-like tumor cells, including SOX2, NANOG, and Oct-4." (PMID 37742009, 2023). "As SOX2 is a pleiotropic transcription factor and an important hallmark of cancer stemness, with functional roles in regulating tumor growth and metastasis, our current findings suggest that increased SOX2 expression may play a role in IL-1RA-promoted OSCC malignancy." (PMID 37461111, 2023). "Interestingly, recent data concerning biomolecular characteristics of GS documented that, although GS has a genetic profile that overlaps with GBM and other neoplasms, it is also true that GS has its genetic mutations, such as MSH6, BRAF, SUZ12, SOX2, and FBXW7." (PMID 38202090, 2023). "However, this single marker was not sufficient to identify the CSC population across all tumors, and a series of additional cell markers, including Nestin and SOX2, have been confirmed to have differences in their ability to self-renew and initiate tumor formation." (PMID 36805592, 2023). "Additionally, targeting newer GSC-specific markers, such as the stem-like cell marker SOX2 that promotes tumour progression or SOCS3, USP8, and DOT1L, which were recently linked to GSC growth, may be more efficient." (PMID 38136335, 2023). "Furthermore, Sox2/Oct4 mediates the expression of interleukin 8 and 6, which, together with the signal peptide peptidase, mediate the shift of macrophage phenotype toward an immune-regulatory profile inhibiting immune response against tumor cells." (PMID 36831383, 2023). "Our data highlight that combinatorial treatment is more effective than single chemotherapy in inhibiting tumor cell growth and invasiveness as well as in reducing number, size and spread in Matrigel of spheroids including the expression levels of their stemness markers Nanog and Sox-2." (PMID 35365193, 2022). "The significant alteration of proliferation and colony formation observed in vitro upon dual FMOD and SOX2 silencing, which contrasted the effects of single-gene depletion, suggests that FMOD and SOX2 functional roles might converge at the induction of tumor growth." (PMID 35737114, 2022). "Therefore, we hypothesized that chronic activation of Sox2 in adult pancreatic epithelial cells would be sufficient to drive fate changes and tumor-related phenotypes." (PMID 35618699, 2022).
tumor (continued). "In addition, the labeling indices of SOX2 and Ki-67 failed to correlate with bone perforation and root resorption caused by the tumor." (PMID 35055392, 2022). "Furthermore, we analysed the effect of SOX2 KO on tumour-initiating activity in vivo." (PMID 35190631, 2022). "Analysis of the tumor compartment in PCPs clearly showed that activation of the MAPK signaling pathway, secondary to BRAFV600E mutation, only occurred in a subset of cells, namely those that exhibit both a marker of precursor dedifferentiation (SOX2) and a proliferation marker (Ki-67)." (PMID 35954494, 2022). "SOX2 controls several characteristics of cancer cells, such as proliferation, epithelium-mesenchymal transition, migration, invasion, metastasis, spherical and colony formation, tumor initiation, and cancer stem cell formation, as well as resistance to apoptosis and chemotherapy." (PMID 36232992, 2022). "In addition, MSCs also reprogram toward CSCs, due to the aberrant changes of tumor microenvironments, which leads to the tumor development through the increased production of Oct4, Sox2, Nanog and the activation of Hedgehog, Wnt, Akt/mTOR, and NF-kB signaling pathways." (PMID 35251985, 2022). "Consequently, this SOX2-IFNI axis is a pivotal signal to mediate tumor immune escape." (PMID 35267473, 2022). "However, SOX2 KO in these cells completely inhibited tumour development." (PMID 35190631, 2022). "Thus, a number of tumor cells and CTCs (CD87+, CD87+CD117+, and CD276+CD117+ and Axl+SOX2+, EGF+SOX2+, and CD87+SOX2+) may be interesting as diagnostic markers of SCLC or indicators of dynamic disease control." (PMID 36142766, 2022). "In addition, SOX2 was reported to control tumor initiation and T-ICs functions." (PMID 35236826, 2022). "In addition, we tested SOX2, Ki67 and Oct4 expression in tumor tissues from different groups." (PMID 35599309, 2022). "It was also obvious that CAFs derived from the AT (αSMA-low, SOX2-high, p16+) or BA (αSMA- and EGFR-high and low SOX2/TP63 ratio) mRNA subtypes could support the growth of both types of tumour cells (primary-tumour ones as well as metastatic-derived ones), while CL and ME CAFs were more specific." (PMID 35565415, 2022). "However, overexpression of ARL4C increased SOX2 in tumor cells." (PMID 33403039, 2021). "Moreover, focus must shift towards slowly eradicating cycling tumor-initiating cells that are resistant to cytotoxic drugs and inhibitors, such as those expressing SOX2+ or high H3K27 methylation and EZH2 expression, and can eventually give rise to recurrent tumors recalcitrant to treatment." (PMID 35054230, 2021). "However, a further study highlighted the favorable effect of inhibiting JMJD3 in limiting tumor progression in vitro and in vivo with a decrease in cell proliferation and pluripotency markers (Nanog, Sox2, and Oct4) and in tumor size and weight after GSK-J4 treatment." (PMID 33478063, 2021). "Thus, TMPRSS4/SLUG–TWIST1/SOX2 axis may represent a novel mechanism involved in the control of tumor progression." (PMID 34809669, 2021). "Since Sox2 and Oct4 are essential for ESC biology; codetection of these proteins enables experimental isolation of CSCs, and targeting of these proteins inhibits tumor growth; thus, associations of YY1 with Oct4 and Sox2 suggest a possible role for YY1 in the CSC phenotype." (PMID 33728560, 2021). "Finally, we found a within-patient difference metric between caveolin-1 and Sox-2 — calculated as the difference between the percentage of positivity of caveolin-1 and Sox-2 in a patient’s tumor sample — to be a strong predictive metric of cetuximab response in these patients with HNSCC." (PMID 34546978, 2021). "Moreover, the chemotherapy effect of irinotecan combined with CQ treatment on the tumor in SW620 SOX2 KD group is better than that in the SW620 control group, suggesting that SOX2 knockdown may increase tumor chemosensitivity in vivo." (PMID 33953166, 2021).